FGFR3 (fibroblast growth factor receptor 3)
Diseases named in the same sentence as FGFR3 in open-access papers (continued):
Sharing a sentence is not in itself a finding about the gene and the disease.
achondroplasia (continued). "Subsequently, in 1998, Wilkin DJ found that FGFR3 mutations occur preferentially during spermatogenesis and that the risk of new point mutations increases with the paternal age increasing, while mutations always in paternal alleles in non-familial cases of achondroplasia." (PMID 38281003, 2024). "The database of Pubmed, Cochrane Library, Wanfang and CNKI were searched with terms of “Achondroplasias” or “Skeleton-Skin-Brain Syndrome” or “Skeleton Skin Brain Syndrome” or “ACH” and “Receptor, Fibroblast Growth Factor, Type 3” or “FGFR3”." (PMID 38281003, 2024). "He tested negative for hypochondroplasia (absence of the p.N540K mutation in FGFR3) but no further investigations were carried out until the parents moved to Belgium and presented in Antwerp with their four-year-old son, where the diagnosis of achondroplasia was made." (PMID 35897040, 2022). "More than 97% of achondroplasia cases result from either a G-to-A or G-to-C transition, where Gly380 (GGG) codon changes to Arg (AGG or CGG) in the FGFR3 transmembrane domain." (PMID 36362274, 2022). "Achondroplasia (ACH), the most common genetic form of short-limb dwarfism, is an autosomal dominant monogenic disorder (MGD) caused by a gain-of-function point mutation in the transmembrane region of fibroblast growth factor receptor 3 (FGFR3)." (PMID 34454631, 2021). "Moreover, it has been suggested that the Oxytocin action in adipocyte differentiation could be mediated by Erk1 / 2 phosphorylation and it would appear that the Oxytocin - FGFR3 / Erk axis plays a key role in the establishment of the phenotype observed in achondroplasia." (PMID 31727132, 2019). "FGFR3 was a hit in our MERLIN-network based prioritization siRNA study and acts as a modulator of the JAK-STAT pathway in growth disorders such as achondroplasia (OMIM)." (PMID 27403523, 2016). "Indeed, in patients suffering from achondroplasia (ACH) and related chondrodysplasia, the substitution of K650E and G380R in FGFR3 protects the surface growth-receptor from being sorted to the lysosomes." (PMID 23900974, 2013). "FGFR3 is the most common aetiological factor of human dwarfism or achondroplasia (ACH)." (PMID 22558096, 2012). "Trials of other investigational therapies for achondroplasia (e.g., FGFR3 inhibitors), preclinical studies, and publications not presenting original research were excluded from the review." (PMID 40821249, 2025). "FGFR3 gene mutation is the major pathogeny of skeletal dysplasia, including achondroplasia (ACH, OMIM: 100,800), hypochondroplasia (HCH, OMIM: 146,000), thanatophoric dysplasia types 1 (TD1) and 2 (TD2), and severe ACH with developmental delay and acanthosis nigricans (SADDAN)." (PMID 36859260, 2023). "In contrast, for several other genes (e.g., FGFR3 and NSD1) a loss of function is associated with tall stature (CATSHL syndrome and Sotos syndrome, respectively), and gain of function with short stature (FGFR3 and CDKN1C; Achondroplasia and Silver-Russell syndrome)." (PMID 34194391, 2021). "Several strategies designed to reduce excessive FGFR3 signaling have been considered as possible treatment to normalize bone growth in achondroplasia, but as of today no approved cure is available." (PMID 33370388, 2020). "A recent study indicates that FGFR3 suppresses NRP-B activity through dephosphorylation of the juxtamembrane domain of NPR-B and the impairment of NPR-B activity is related to the impaired skeletal growth shown in achondroplasia." (PMID 33002060, 2020). "BGJ398 also inhibited FGFR3 downstream signalling pathways, including MAPK, SOX9, STAT1, and PLCγ, in the growth plates of Fgfr3Y367C/+ mice and in cultured chondrocyte models of achondroplasia." (PMID 32144686, 2020). "In 2014, intraperitoneally injected statins rescued long bone growth in a mouse model of achondroplasia Fgfr3Ach but a later study demonstrated that statins do not inhibit FGFR3 signalling in chondrocytes." (PMID 32144686, 2020).
achondroplasia (continued). "Two developmental defects, Hunter-Thompson chondrodysplasia and fibroblast growth factor-receptor 3 (FGFR3) achondroplasia, both of which afflict systemic load-bearing joints but not the TMJ, provide further evidence of the uniqueness of the TMJ." (PMID 27257443, 2016). "Since heterozygous achondroplasia with a similarly severe phenotype has never been reported previously, we then collected parental blood and fetal amniotic fluid exfoliated cells to perform whole exome sequencing of FGFR3 gene." (PMID 37076826, 2023). "Skull development was not evaluated in the BMN 111-treated achondroplasia mouse model, but as expression of the mutant FGFR3 is targeted only to cartilage using a collagen 2 promoter sequence, effects on intramembranous skull bones that do not develop from cartilage are secondary." (PMID 30048539, 2018). "Recently, gain-of-function mutations in the transmembrane domain of FGFR3 has been described associated with an aberrant negative regulation, leading to the development of achondroplasia-group disorders, including achondroplasia (ACH), hypochondroplasia (HCH) and thanatophoric dysplasia (TD)." (PMID 28679403, 2017). "Overactive fibroblast growth factor receptor 3 (FGFR3) signaling drives pathogenesis in a variety of cancers and a spectrum of short-limbed bone dysplasias, including the most common form of human dwarfism, achondroplasia (ACH)." (PMID 37824212, 2023). "Molecular level diagnosis of Nepalese Achondroplasia is not yet done, thus, in this study FGFR3 gene of five Nepalese ACH cases are analyzed." (PMID 30381765, 2018).
urothelial carcinoma (115 papers, 2011 to 2026). A malignant neoplasm derived from the transitional epithelium of the urinary tract (urinary bladder, ureter, urethra, or renal pelvis). "In urothelial carcinoma, FGFR3 mutations are most prevalent, with an overall frequency of approximately 15–20%; detection rates reach 40–50% in non-muscle-invasive bladder cancer but decline to 10–15% in muscle-invasive or metastatic disease." (PMID 41514604, 2025). "A retrospective study from van Rhijn et al19 detected FGFR3 mutations in 77% of pTa, 31% pT1, and 15% of pT2+ urothelial carcinomas, based on 260 tumors." (PMID 41097827, 2025). "The FGFR RGQ RT-PCR kit (Qiagen) is FDA-approved for detecting FGFR2/FGFR3 fusion variants in urothelial carcinoma (FGFR2-BICC1, FGFR2-CASP7, FGFR3-TACC3, FGFR3-BAIAP2L1)." (PMID 39583123, 2024). "Erdafitinib has been approved for patients with urothelial carcinoma harboring FGFR2 or FGFR3 mutations." (PMID 39421453, 2024). "The pathogenetic pathway of superficial noninvasive urothelial carcinoma is characterized by FGFR3, tyrosine receptor, HRAS and PI3KCA mutations." (PMID 39118085, 2024). "For instance, FGFR3 point mutations and less frequent FGFR3 rearrangements are found in 20% of advanced urothelial carcinomas, while FGFR2/3 fusions are of particular interest in cholangiocarcinomas, in which they occur in 14% of cases." (PMID 38347643, 2024). "Erdafitinib has been approved for treating urothelial carcinoma patients with FGFR2/FGFR3 mutations,23and clinical studies are underway for other solid tumors." (PMID 39583123, 2024). "Studies have shown FGFR-3 mutation to be among the most common mutated oncogene in urothelial carcinoma overall." (PMID 37370778, 2023). "Whole-exome sequencing results for the six cases of the large, nested variant of urothelial carcinoma showed 3 cases (50%) to harbor positive activating mutation in FGFR-3." (PMID 37370778, 2023). "FGFR-3 mutations have been reported in about 75% of noninvasive urothelial carcinoma and about 15–20% of high-grade tumors." (PMID 37370778, 2023). "In urothelial carcinoma, activated FGFR3 phosphorylates NEDD4 and further regulates Lys48‐linked ubiquitination of PD‐L1 to activate CD8+ T cell infiltration and antitumor activity." (PMID 37143582, 2023). "A phase II study FIGHT-201 (NCT02872714) was conducted to evaluate pemigatinib in patients (n = 64) with metastatic or surgically-unresectable urothelial carcinoma with FGFR3 mutations or fusions progressed after systemic treatment." (PMID 37681152, 2023). "The luminal papillary subtype of urothelial carcinoma is associated with FGFR3 genetic mutations, which is consistent with the high rate of FGFR3 alterations observed in the low necroptotic module." (PMID 37000317, 2023). "Its receptor (FGFR3) shows mutations and overexpression in a large proportion of urothelial carcinomas and even represents a target for therapy with tyrosine kinase inhibitors." (PMID 36843751, 2023). "Our results indicates that the FGFR-3 mutation is among the most common mutated oncogene in urothelial carcinoma, and it is even more common in the LNVUC." (PMID 37370778, 2023). "According to the main findings, UTUC represent a particular subtype of urothelial carcinoma frequently associated with activated FGFR3 signaling, a luminal–papillary phenotype and a T-cell-depleted microenvironment." (PMID 35200559, 2022). "Mutations and fusions in Fibroblast Growth Factor Receptor 3 (FGFR3) occur in 10–20% of metastatic urothelial carcinomas and confer sensitivity to FGFR inhibitors." (PMID 35501832, 2022).
urothelial carcinoma (continued). "In the phase II BLC2001 trial, erdafitinib brought an ORR of 40% to patients with urothelial carcinoma susceptible to FGFR3 or FGFR2 genetic alterations whose diseases progressed during or following at least one line of prior platinum‐containing chemotherapy." (PMID 36254250, 2022). "FGFR3 dysregulation via mutation, overexpression, or both have been noted in 54% of invasive urothelial carcinomas (UCs)." (PMID 35406567, 2022). "Point activating mutations in the FGFR3 gene are found in approximately 80% of urothelial carcinomas and in 15% of MIBC cancers." (PMID 35326568, 2022). "Urothelial carcinomas and their metastases, in which this mutation was discovered, respond well to targeted therapy with FGFR3 inhibitors." (PMID 35326568, 2022). "More recently, erdafitinib, a pan-FGFR targeted inhibitor, was approved by the FDA in April 2019 for advanced urothelial carcinoma with FGFR3 hotspot mutation like S249C as the first molecularly targeted therapy." (PMID 34160364, 2021). "The in vivo activity of Co(acac)2LPon was confirmed in an FGFR3 mutation-dependent urothelial carcinoma xenograft background." (PMID 34046181, 2021). "In this regard, in a study of dovitinib in 13 patients with Bacillus Calmette–Guerin (BCG)-refractory urothelial carcinoma and FGFR3 alterations, three patients had FGFR3 mutations." (PMID 32962091, 2020). "Activation point mutations of FGFR3 are found in up to 80% of low-grade and staged urothelial carcinomas (UC) of the bladder." (PMID 33117683, 2020). "In urothelial carcinoma, the gatekeeper mutations FGFR3 V443L, V443M, and L496V, were detected in cfDNA in 3 of 50 patients receiving erdafitnib." (PMID 35582593, 2019). "TERT promoter mutations are shown to be tightly associated with the presence of FGFR3 mutations in urothelial carcinomas (UC)." (PMID 28416747, 2017). "Only a few mutational hot spots account for all FGFR3 mutations detected in urothelial carcinomas and skin tumors (epidermal nevi and seborrheic keratoses) so far." (PMID 27999595, 2016). "While mutations in tumor suppressor genes allow for uncontrolled cell proliferation and cell cycle progression, the driver mutation present in many urothelial carcinomas is mutation or gene fusion of the fibroblast growth factor receptor 3 (FGFR3)." (PMID 25909217, 2015). "Urothelial carcinoma cells with FGFR3 mutations that are insensitive to pan-FGFR inhibitors (those containing the FGFR3S249C or FGFR3Y375C mutations) were found to be sensitive to Hsp90 inhibitors." (PMID 25909217, 2015). "Mutations in Fibroblast Growth Factor Receptor-3 (FGF3R) are more often found in low grade urothelial carcinoma (LGUC) than in high grade urothelial carcinoma (HGUC)." (PMID 24018887, 2013). "Activating mutations in FGFR3 are found at high frequency in low-grade non-invasive (stage Ta) urothelial carcinoma (UC) and several studies have highlighted activated FGFR3 as a potential therapeutic target in this subgroup." (PMID 22701738, 2012). "Mutations in FGFR3 are known to be associated with urothelial carcinoma and have a positive predictive value of 95% when detected in patients with no history of TCC." (PMID 22873290, 2012). "Activating mutations and/or overexpression of FGFR3 are common in urothelial tumours with low malignant potential and low-stage and -grade urothelial carcinomas (UCs) and are associated with a lower risk of progression and better survival in some subgroups." (PMID 22899908, 2012). "Urothelial carcinoma (UC) is characterized by frequent gene mutations of which activating mutations in FGFR3 are the most frequent." (PMID 21533174, 2011). "Additionally, a case of PRNRP with KRAS mutation was also reported synchronously with urothelial carcinoma with a distinct FGFR3/KDM6A mutation." (PMID 40860802, 2025).
urothelial carcinoma (continued). "Given the shared mutations between skeletal dysplasia associated with FGFR3 and FGFR3-dependent cancers like urothelial carcinomas, cervical carcinomas, and multiple myeloma, some therapeutic strategies of ACH have been co-opted conceptually from the oncological field." (PMID 40256430, 2025). "Furthermore, certain genes are associated with the staging and grading of urothelial carcinoma; among these, FGFR3 is the most commonly mutated gene in UTUC, with a mutation frequency as high as 74%, and this frequency can reach 92% in low-grade tumors." (PMID 39664176, 2024). "Additionally, in some urothelial carcinoma patients with an FGFR3 mutation, such as FGFR3 N540K, V553M, V555L/M, or L608V, and in 50% with FGFR4-mutant hepatocellular carcinoma, resistance has been observed." (PMID 38791529, 2024). "Therefore, we evaluated the FGFR3 mutation rate and its clinical significance in urothelial carcinoma (UC) using next-generation sequencing." (PMID 38592174, 2024). "Moreover, FGFR3 gene mutations have been detected in 18% of urothelial carcinomas, 14% of uterine carcinosarcomas, 5% of esophageal cancers, 5% of ovarian cancers and 4% of endometrial cancers." (PMID 39118085, 2024). "Erdafitinib has been approved for patients with urothelial carcinomas with select FGFR3 mutations." (PMID 37064128, 2023). "Our study provides further evidence of the promising role for FGFR-3 in the diagnosis and treatment of the large, nested variant of urothelial carcinoma, possibly implicating other targetable pathways compared to random unselected variants of urothelial carcinoma." (PMID 37370778, 2023). "Moreover, in the resistant luminal-excluded subtype, the investigators demonstrated that inhibition of KDM5B enhances immunogenicity in FGFR3-mutated urothelial carcinoma cells." (PMID 37296985, 2023). "Overall, all of these studies document a high incidence of FGFR-3 mutations in urothelial carcinoma, and they support that the LNVUC variant may exhibit an even higher incidence of FGFR-3 mutations especially in more pure histological type." (PMID 37370778, 2023). "This receptor could potentially facilitate BoNT/A uptake in the urothelium as it has been shown that FGFR3 is expressed in the urothelium and mutations in the FGFR3 gene contribute to the development of urothelial carcinoma." (PMID 35051030, 2022). "As it appears, FGFR3 mutations are not only limited to targeted therapy in urothelial carcinoma." (PMID 35326568, 2022). "Very interestingly, in urothelial carcinoma, where FGFR3-activating mutations are most frequent (see before), it could be shown that the presence of a point mutation leads to strong overexpression of the mutant protein." (PMID 36231142, 2022). "In addition to the presence of FGFR3 amplification and mutations in urothelial carcinoma, FGFR2/3 fusions have also been detected." (PMID 33655556, 2021). "The fibroblast growth factor receptor 3 (FGFR3) gene mutation is highly prevalent in urothelial carcinomas, and the mutant FGFR3 promotes malignant development by over-stimulating the RAS-mitogen-activated protein kinase and phosphatidylinositide-3 kinase–AKT pathway." (PMID 28416747, 2017). "The fibroblast growth factor (FGF) family of transmembrane tyrosine kinase receptors mediates proliferation in response to FGF stimulation and has been implicated in the pathogenesis of urothelial carcinoma: fibroblast growth factor receptor 3 (FGFR3) is frequently mutated or overexpressed in NMIBC." (PMID 29165379, 2017).